CD109 (CD109 molecule)
Description:
Modulates negatively TGFB1 signaling in keratinocytes.
Synonyms: CPAMD7; HPA-15; FLJ38569; DKFZp762L1111; p180; r150
Tractability: Antibody: UniProt places it where antibodies can reach, with high confidence; its Gene Ontology location is reachable by antibodies, with high confidence; UniProt predicts a signal peptide or a membrane-spanning region; the Human Protein Atlas places it where antibodies can reach. PROTAC: ubiquitination databases record sites on it; its protein half-life has been measured.
Gene: Protein-coding gene on chromosome 6 (73,695,785 to 73,828,316, forward strand). Ensembl gene ENSG00000156535.
Subcellular location: Cell membrane
Subcellular location (Human Protein Atlas): Plasma membrane; Cytosol
Pathways (Reactome):
Hemostasis: Platelet degranulation
Metabolism of proteins: Post-translational modification: synthesis of GPI-anchored proteins
Gene Ontology:
Molecular function: endopeptidase inhibitor activity
Biological process: negative regulation of transforming growth factor beta receptor signaling pathway; negative regulation of wound healing
Cellular component: cell surface; plasma membrane; extracellular region; platelet alpha granule membrane
Genetic constraint (gnomAD): Loss-of-function variants: 80 observed, 88.27 expected, observed/expected ratio (o/e) 0.91, 90% interval 0.76 to 1.09. The upper end of that interval is the gene's LOEUF score, 1.09, which puts it in group 4 of 6, group 1 being the genes least tolerant of losing a copy. Missense variants: 1,144 observed, 1,143.9 expected, observed/expected ratio (o/e) 1, 90% interval 0.95 to 1.05. Synonymous variants: 410 observed, 425.43 expected, observed/expected ratio (o/e) 0.96, 90% interval 0.89 to 1.05.
Homologues: Orthologues: chimpanzee CD109 (99% identical), macaque CD109 (90% identical), dog CD109 (88% identical), pig CD109 (85% identical), guinea pig CD109 (78% identical), rabbit CD109 (76% identical), mouse Cd109 (72% identical), rat Cd109 (70% identical), tropical clawed frog cd109 (47% identical), zebrafish cd109 (35% identical), Caenorhabditis elegans tep-1 (30% identical), Drosophila melanogaster Tep2 (28% identical), and 3 more. Paralogues in human: CPAMD8 (31% identical), A2M (28% identical), PZP (27% identical), A2ML1 (26% identical), C4A (21% identical), C4B (21% identical), C3 (21% identical), C5 (20% identical).
Diseases named in the same sentence as CD109 in open-access papers:
CD109 is named in the same sentence as 119 diseases in open-access papers, as found by Europe PMC text mining. Sharing a sentence is not in itself a finding about the gene and the disease. The quoted sentences say what the papers report.
squamous cell carcinoma (18 papers, 2012 to 2025). A carcinoma arising from squamous epithelial cells. "Elevated expression of CD109 has been implicated in the progression of cancers including squamous cell carcinoma, glioblastoma, prostate carcinoma, basal-like breast carcinoma, and certain adenocarcinomas and sarcomas." (PMID 39990858, 2024). "It has been implicated in breast cancer (where RNAi knockdown of CD109 suppressed malignant growth and CD109 shed from the cell surface has a pro-growth function), squamous cell carcinoma of the oral cavity and is upregulated in various tumour cell lines including GBM cell lines." (PMID 22311740, 2012). "CD109's involvement in cancers such as lung adenocarcinoma, glioblastomas, hepatocellular carcinomas, breast cancer, leukemia, and squamous cell carcinomas highlights its significant impact on immune responses and oncogenic process." (PMID 39990858, 2024). "Together, these findings highlight a potential clinical utility for targeting CD109 in squamous cell carcinoma." (PMID 35954339, 2022). "Increased levels of CD109 transcript expression levels have been seen in the squamous cell cancers of the oesophagus, cervix, and lung." (PMID 35774118, 2022). "CD109 is a glycoprotein with a glycosylphosphatidylinositol (GPI) anchor that is overexpressed in squamous cell carcinomas of the lung, esophagus, uterus, and oral cavity." (PMID 34630565, 2021). "In particular, CD109 immunoreactivity was significantly higher in the squamous cell carcinoma cases than in the normal–benign cervical tissue cases (P1 < 0.0001, Mann–Whitney test) and adenocarcinoma cases (P2 = 0.0007, Mann–Whitney test)." (PMID 32507856, 2020). "Together, our findings suggest that hBM-MSCs inhibit the malignant traits of squamous cell carcinoma cells by a paracrine effect via released factors and that CD109 released from hBM-MSCs, at least partially, mediates these effects." (PMID 29221155, 2017). "CD109 is a glycosylphosphatidylinositol-anchored glycoprotein that is highly expressed in several types of human cancers, particularly squamous cell carcinomas." (PMID 27756876, 2016). "Although high levels of CD109 have been reported in glioblastoma and squamous cell carcinoma cell lines, to our knowledge our findings represent the first description of the upregulation of CD109 in pancreatic cancer." (PMID 25635161, 2014). "Further investigations using clinical samples from patients with carcinomas such as squamous cell carcinomas are needed to verify the usefulness of CD109 in cancer management." (PMID 24400073, 2014). "CD109, a glycosylphosphatidylinositol-anchored glycoprotein, is expressed at high levels in some human tumors including squamous cell carcinomas." (PMID 24400073, 2014). "In squamous cell carcinoma (SCC), CD109 is essential for tumor progression and is associated with increased EGFR expression/stabilization, and enhanced EGFR/Akt signaling, which are crucial for maintaining epithelial morphology and cellular stemness, as shown by us and others." (PMID 39990858, 2024). "We also show that CD109 acts by associating with another protein called the epidermal growth factor receptor (EGFR), stabilizing its levels and promoting its action, leading to increased progression of squamous cell carcinoma." (PMID 35954339, 2022). "However, as a co-receptor of the transforming growth factor (TGF)-β receptor (TGF-βR), CD109 was reported to negatively regulate the epithelial-to-mesenchymal transition (EMT) by antagonizing TGF-β signaling in squamous cell carcinomas." (PMID 33375719, 2020). "In the current study, we examined whether hBM-MSCs regulate the malignant properties of squamous cell carcinoma cells, and whether CD109 plays a role in mediating the effect of hBM-MSCs on cancer cells." (PMID 29221155, 2017).
squamous cell carcinoma (continued). "Although the literature reports that CD109 is highly expressed in squamous cell carcinoma, our previous study identified that CD109 overexpression was specifically associated with poor survival probability in patients with lung adenocarcinoma but not with squamous cell carcinoma." (PMID 33375719, 2020). "CD109’s secretion by human bone marrow mesenchymal stem cells reduces EMT and diminishes the stem cell-like properties of squamous cell carcinoma induced by TGF-β." (PMID 39990858, 2024). "CD109 secretion by human bone marrow mesenchymal stem cells lessens EMT and diminishes the stem cell-like properties of squamous cell carcinoma induced by TGF-β." (PMID 39990858, 2024). "There is increasing evidence that the expression of CD109, a GPI-anchored cell surface protein is dysregulated in squamous cell carcinoma (SCC)." (PMID 31695056, 2019). "Subtypes of GBCs tissues including adenocarcinoma (AC), squamous cell carcinoma (SCC), and adenosquamous carcinoma (ASC) were examined on TMAs by immunohistochemical staining with a CD109 antibody." (PMID 29625613, 2018). "CD109 expression was examined in human lung cell carcinomas by quantitative RT-PCR, which showed a significantly higher expression of CD109 in squamous cell carcinomas, but not in adenocarcinomas, large-cell carcinomas or small-cell carcinomas." (PMID 29625613, 2018). "We found that CD109 is specifically expressed in malignant squamous cells in squamous cell carcinomas (86.7%) and adenosquamous carcinomas (91.7%), but not in adenocarcinomas or normal gallbladder tissues." (PMID 26249215, 2015). "For example, high levels of CD109 expression were observed by immunohistochemistry in squamous cell carcinomas and premalignant lesions of the oral cavity but not in normal tissue, suggesting that CD109 is useful in predicting transformation of premalignant lesions into cancer." (PMID 29731998, 2018).
glioblastoma (16 papers, 2013 to 2025). The most malignant astrocytic tumor (WHO grade IV). "In recent years, the interplay between members of the HER family receptors with EGFRvIII and cancer stem cell biomarkers like CD44 and CD109 have been associated with the aggressive nature of glioblastoma." (PMID 40227788, 2025). "Ablation of CD109 in glioblastoma models leads to a loss of stemness and a phenotypic shift to a more differentiated astrocyte-like cell." (PMID 35456993, 2022). "Serum-induced cell differentiation caused a rapid and global downregulation of the GSC markers and CD109, supporting the association between CD109 and glioblastoma cell stemness." (PMID 33986188, 2021). "In accordance with these previous observations, we confirmed a strong association of CD109 with the MES subtype of glioblastoma across the independent data sets and poor survival in patients with gliomas." (PMID 33986188, 2021). "It has been recently suggested that CD109 expression associates with the MES glioblastoma subtype in TCGA data set." (PMID 33986188, 2021). "We reasoned that the loss of CD133 mRNA (CD133low) and gain of CD109 (CD109high) were indicative of the E-to-C progression in glioblastoma." (PMID 33392508, 2020). "Furthermore, it has been reported that CD109 is highly expressed in various malignant tumors, including lung, liver, pancreas, esophagus, uterus, oral cavity, breast cancer, glioblastoma, and several types of sarcomas, and is associated with a poor prognosis." (PMID 37373457, 2023). "Therefore, in this study for the first time, the expression level of all members of the HER family, EGFRvIII, CD44, and CD109 was determined at different cut of values in patients with glioblastoma as well as their association with the patient’s overall survival." (PMID 40227788, 2025). "Taken together, our results suggest that the co-expression of different members of the HER family, with EGFRvIII, CD44, and CD109 is common in patients with glioblastoma." (PMID 40227788, 2025). "In this study, our aim was to examine the relative expression and prognostic significance of all members of the HER family, the type III EGFR mutant (EGFRvIII), and the putative stem cell markers CD44 and CD109 in patients with glioblastoma." (PMID 40227788, 2025). "Another factor associated with tumour progression is CD109 and the interaction of CD109 with STAT3 has been shown to drive glioblastoma stem cell plasticity and chemoresistance via STAT signalling." (PMID 40227788, 2025). "In one study, the high expression of CD109 expression has been correlated with increased activity of the STAT3 pathways and causing high proliferation of glioblastoma cells." (PMID 40227788, 2025). "In glioma stem cells (known to drive the propagation and therapy resistance of glioblastomas), CD109 interacts with glycoprotein 130 (GP130) to activate the IL-6/STAT3 pathway." (PMID 39990858, 2024). "It has been reported that the CD109/STAT3 signaling axis is a mediator of chemoresistance in glioblastoma stem cells." (PMID 37373457, 2023). "The transcriptomic analysis also revealed that GZ17-6.02 treatment results in suppression of several genes implicated in glioblastoma growth and invasion, such as EGR1, ASCL1, CD109, ABCG2, and CDH5." (PMID 35456993, 2022). "This proof of concept indicates that targeting CD109/STAT3 axis sensitizes the highly resistant GSCs to chemotherapy, supporting an important role for CD109 in conferring chemoresistance of glioblastoma." (PMID 33986188, 2021). "To profile CD109 expression within glioblastoma subtypes, we analyzed 17 individual glioblastoma data sets where the subtype-specific information was available, consisting of 2100 patient samples in total." (PMID 33986188, 2021). "The importance of the CD109 expression in glioblastomas and treatment response has been recently suggested by Minata and colleagues in the context of radiotherapy." (PMID 33986188, 2021).
glioblastoma (continued). "To get a more comprehensive view of alterations in global gene expression profiles and their relationship with different glioblastoma subtypes, we profiled the control and CD109-silenced GSCs using RNA-Seq." (PMID 33986188, 2021). "Our data indicate that therapeutic targeting of CD109/STAT3 axis in combination with chemotherapy provides a relevant therapeutic approach to increase the effectiveness of glioblastoma treatment." (PMID 33986188, 2021). "The analysis of these groups revealed significant association between CD109 expression and p-STAT3 (P = 0.002) and Ki-67 (P = 0.041) only in glioblastomas." (PMID 33986188, 2021). "Together these results demonstrate a vital role for CD109/STAT3 axis in the maintenance of glioblastoma cell stemness." (PMID 33986188, 2021). "CD109 was also found to be upregulated in glioblastoma after radiation induced damage and stabilized the cancer stem cell niche." (PMID 33738281, 2021). "Specifically, we tested if PLAGL1 as a TF binds to the promoter region for the CD109 gene in glioblastoma edge-derived cells." (PMID 33392508, 2020). "To expand upon our previous studies, we used CD133 and CD109 mRNA expression profiles to indicate edge-ness and core-ness, respectively, a concept that we validated with 19 paired glioblastoma edge- and core-samples." (PMID 33392508, 2020). "In this study, we used CD133 and CD109 mRNA expression dynamics as a reference to indicate the E-to-C progression in glioblastoma." (PMID 33392508, 2020). "Consistently, Pearson’s correlation analysis of the 37 glioblastoma paired samples indicated a strong linear relationship between CD109 and PLAGL1 relative expression (r = 0.7, P < .05)." (PMID 33392508, 2020). "High expression of CD109 antigen is associated with poor prognosis of soft tissue sarcoma, and CD109+ endothelial cells is a prognostic indicator for glioblastomas." (PMID 26025379, 2015). "Before treatment, significantly higher levels of CD109+ CECs and viable CD109+CECs were found in breast cancer patients and glioblastoma patients compared to healthy controls, and their number significantly decreased after treatment." (PMID 25506915, 2014). "In this work we report that CD109 is a potential useful prognostic marker in glioblastoma patients, and that its role in cancer angiogenesis need to be investigated in different tumor setting." (PMID 25506915, 2014). "CD109+CECs were 26±20/mL in healthy subject (n = 50), 62±43/mL in metastatic breast cancer patients (n = 66, p<0.0001) and 101±84/mL in glioblastoma patients (n = 134, p<0.0001) before treatment." (PMID 25506915, 2014). "After treatment CD109+CECs and viable CD109+CECs were 52±42/mL and 15±20/mL respectively in breast cancer patients, and 64±60/mL and 35±30/mL in glioblastoma patients." (PMID 25506915, 2014). "Taken together our results suggest that CD109 represent a rare population of circulating tumor endothelial cells, that play a potentially useful prognostic role in patients with glioblastoma." (PMID 25506915, 2014). "The fraction of apoptotic/necrotic CD109+CECs was 71±18% in healthy subject, 51±18% in breast cancer patients and 60±21 in glioblastoma patients." (PMID 25506915, 2014). "Therefore, further research is needed to understand the exact mechanisms by which CD109 expression and its co-expression with other biomarkers contributing to tumour progression in glioblastoma." (PMID 40227788, 2025). "However, there has been no study of the relative expression and prognostic significance of all members of the HER family with EGFRvIII, CD44, and CD109 in patients with glioblastoma." (PMID 40227788, 2025). "CD109 increased the levels of p-STAT3 in keratinocytes and promoted the formation of lung adenocarcinoma metastasis via JAK/STAT3 pathway whereas in glioblastomas such association has remained unexplored." (PMID 33986188, 2021).
glioblastoma (continued). "CD109-silenced GSCs showed markedly reduced p-STAT3 levels compared with the nontargeted controls independently of the glioblastoma subtype, thus verifying the observed association between CD109 and p-STAT3 in the patient samples." (PMID 33986188, 2021). "Importantly, genetic or pharmacologic targeting of CD109/STAT3 axis sensitized the GSCs to chemotherapy, suggesting that targeting CD109/STAT3 axis has potential to overcome therapy resistance in glioblastoma." (PMID 33986188, 2021). "Taken together these results suggest that CD109 could represent a rare population of circulating tumor endothelial cells, that play a potentially useful prognostic role in patients with glioblastoma." (PMID 25506915, 2014). "Given the tumor-promoting role of CD109 and of IL-6 in SCC and the recent findings that CD109 potentiates JAK/STAT3 signaling in lung adenocarcinoma and glioblastoma cells, it was important to establish whether CD109 regulates IL6Rα signaling in SCC and determine the mechanisms involved." (PMID 40317079, 2025). "It was recently reported that CD109 interacts with GP130, a component of the IL-6 receptor complex, in glioblastoma cells." (PMID 40317079, 2025). "CD109-mediated augmentation of EGF signaling has also been reported in lung adenocarcinoma and in glioblastoma cells." (PMID 40317079, 2025). "The interaction between CD109 and GP130 is known to increase STAT3 phosphorylation, thereby promoting stemness properties, tumorigenicity, and chemoresistance of glioblastoma stem cells and metastasis of lung adenocarcinomas." (PMID 37373457, 2023). "In brief, high CD109 expression is a biomarker of malignant glioblastomas, correlating with an increased activity of the STAT3 pathway and highly proliferating glioblastoma cells." (PMID 33986188, 2021). "E-to-C axis represents an ongoing lethal process in primary glioblastoma contributing to its recurrence, partly in a PLAGL1/CD109-mediated mechanism." (PMID 33392508, 2020). "A recent report provides evidence to indicate CD109 enhances EGF signaling while attenuating TGF-β signaling, in SK-MG1 glioblastoma cells." (PMID 31695056, 2019). "Significantly higher levels of CD109+CECs, CD146+CECs, viable CD109+CECs and viable CD146+CECs (P = 0.0001) were found at baseline in breast cancer patients and glioblastoma patients compared to healthy controls." (PMID 25506915, 2014). "The overexpression of CD44 has been reported in many studies but not so much for CD109 in glioblastoma patients." (PMID 40227788, 2025). "CD109 negatively regulates TGF-β1 signaling and enhances EGF signaling in glioblastoma cells, and might represent a critical link in the balance of signaling between these two oncogenic pathways that control inflammatory responses, cell migration and invasion." (PMID 39990858, 2024). "Furthermore, it has been reported that the activation of the signal transducer and activator of transcription 3 (STAT3) through the interaction of CD109 and glycoprotein 130 (GP130) promotes plasticity and chemoresistance in glioblastoma stem cells." (PMID 37373457, 2023). "Analysis of The Cancer Genome Atlas (TCGA) glioblastoma data set demonstrated increased CD109 mRNA expression in glioblastomas compared with the nontumor tissue, supporting the relationship between CD109 and tumorigenicity." (PMID 33986188, 2021). "Our results suggest that targeting the CD109/STAT3 axis in GSCs could provide means to overcome therapeutic resistance and improve treatment efficacy in patients with glioblastoma." (PMID 33986188, 2021). "Therefore, we performed an analysis of the mRNA expression of CD109 and the key mediators of the STAT3 signaling pathway (IL6ST/GP130, STAT3, and IL6) in the Human Glioblastoma Cell Culture (HGCC) data set." (PMID 33986188, 2021).